INS (insulin)
Diseases named in the same sentence as INS in open-access papers (continued):
Sharing a sentence is not in itself a finding about the gene and the disease.
diabetes (continued). "Current interventions for insulin resistance and diabetes, focus on four mechanisms: 1) enhancements of insulin secretion, 2) reduction of hepatic glucose production, 3) delay of carbohydrate absorption and 4) improvement in insulin sensitivity." (PMID 28640857, 2017). "Although the dogs in this study were receiving insulin, all were undergoing evaluation for poor diabetes control at the time of sample collection." (PMID 28842637, 2017). "Diabetes is characterized by hyperglycaemia (fasting plasma glucose ≥126 mg/dL [7 mmol/L]) due to insufficient insulin production or insulin resistance." (PMID 29209160, 2017). "Using a diabetes-specific specific stimulus (e.g., islet peptide, insulin) to stimulate T cells to assess the expression of PD-1 is a next step." (PMID 28877189, 2017). "In contrast, it is increasingly common for population-based studies to collect physiologic data, including blood glucose and insulin levels that can be used to screen for diabetes and evaluate insulin resistance and sensitivity." (PMID 28253317, 2017). "In terms of the diagnostic criteria for diabetes, the lowest and the highest prevalence rates are related to DAD (7%) and the history of insulin therapy (13%)." (PMID 28503277, 2017). "No other metabolic or baseline characteristics including age, BMI, surrogate markers of glycemic control, duration of diabetes, and insulin doses correlated with improvement in MAGE." (PMID 28725273, 2017). "STZ-induced diabetes can be alleviated by promoting the secretion of insulin and/or improving insulin sensitivity." (PMID 28935866, 2017). "Diabetes is widely explained as a physiopathological situation involving difficulty in promoting glucose uptake by peripheral tissues, mainly due to impaired insulin secretion and/or low insulin sensitivity in the glucose uptake tissues." (PMID 27087124, 2016). "Insulin signaling in the placenta was reported to be impaired in pregnancies complicated by obesity and diabetes." (PMID 27196053, 2016). "Insulin is a key hormone of human metabolism with major therapeutic importance for both types of diabetes." (PMID 26792393, 2016). "Since T2DM is the most common type of diabetes, improving insulin sensitivity is an important clinical goal." (PMID 27738449, 2016). "Forty-nine percent of IR-SPIDDM patients had been started insulin treatment at the diagnosis of GADAb-positive diabetes." (PMID 27177031, 2016). "Insulin remains the most efficacious drug to optimise glycaemic control in patients with diabetes and is comparatively safe across the stages of NAFLD." (PMID 26856933, 2016). "New-onset diabetes was identified based on the history of diabetes, currently treated with insulin or oral hypoglycemic agents, or having a fasting blood glucose concentration ≥7.0 mmol/L during the 2010 to 2011 and 2012 to 2013 surveys." (PMID 27559955, 2016). "ZnT8-deficient mice have impaired insulin secretion and crystal formation in diabetes mellitus and rapidly clear insulin from the liver." (PMID 27872866, 2016). "This study aimed to investigate the alteration of Neuropeptide Y (NPY) in the hypothalamus and its correlation with insulin, leptin and ghrelin during the development of a rat model of type 2 diabetes mellitus." (PMID 27867820, 2016). "A low proportion of diagnosed diabetes cases received insulin in our rural and least developed sites." (PMID 26913752, 2016). "Eventually, of course insulin release cannot keep up with the resistance and insulin levels fall, glucose rises and diabetes occurs." (PMID 27306890, 2016). "The clinical diagnosis of MODY has been based upon the following criteria: family history of diabetes, insulin independence, and onset by age 25 yr." (PMID 26059258, 2016). "Although the pharmacological treatment of diabetes mellitus is based on oral hypoglycemic agents and insulin injection, in many countries, various antioxidant plants are used traditionally as an alternative strategy for the treatment of diabetes." (PMID 26927038, 2016).
diabetes (continued). "A petroleum ether extract of NS exhibits insulin-sensitizing activity and the mechanism of NS extract in the control of diabetes has ben shown to be through controlled insulin release." (PMID 27068721, 2016). "Multiple regression analysis showed the B-DDS score was positively correlated with marital status (p=0.0230), use of diet and physical activities for diabetes management (p=0.0180), and use of insulin therapy (p=0.0030)." (PMID 27759822, 2016). "Further experiments showed that blocking glucagon receptors in typical mice with diabetes reduces blood sugar, but only if there is some insulin left in their bodies." (PMID 27092792, 2016). "Of the five serious adverse events attributable to prednisolone, two patients were diagnosed with pulmonary TB and were treated with anti-tuberculous drug and two developed diabetes, one requiring insulin and the second managed with oral hypoglycaemic." (PMID 26919207, 2016). "This study involved 28900 UK resident patients with insulin-treated diabetes who were less than 50 years old at the diagnosis of diabetes." (PMID 28197516, 2016). "A possible explanation relies on the observation that males are generally more insulin resistant than females, thus requiring a smaller weight gain than females for them to develop diabetes." (PMID 27300299, 2016). "Cinnamon has been reported to reduce blood sugar in patients with diabetes, and studies have shown that agents that enhance insulin sensitivity or reduce circulating insulin levels also lower blood pressure." (PMID 27158555, 2016). "A recent study showed that in patients recovering from diabetes after bariatric surgery, INSR-B levels (in visceral fat) correlated with weight loss and negatively correlated with blood insulin levels." (PMID 27526875, 2016). "SCAAR registry had the highest number of patients with insulin-treated diabetes mellitus (ITDM) followed by the TUXEDO study." (PMID 27057888, 2016). "Most patients with T1D would require multiple daily doses of insulin or a continuous subcutaneous insulin infusion (CSII) pump for control of diabetes." (PMID 28702252, 2016). "Diabetes mellitus, one of the most common chronic metabolic diseases, occurs when the pancreas produces insufficient levels of insulin or when the body cannot use the insulin effectively." (PMID 27136568, 2016). "Lastly, over the 12-month study period, we had access to limited paired data to assess the progression of insulin sensitivity/type 2 diabetes mellitus and to correlate these results with clinic visit frequency." (PMID 28058253, 2016). "T1DM is an autoimmune-mediated disease characterized by selective destruction of insulin-producing pancreatic β-cells, resulting in the need for lifelong administration of exogenous insulin for patient survival, and represents 5–10% of all cases of diabetes." (PMID 27699180, 2016). "Induction of diabetes with STZ resulted in approximately 11-fold reduction in serum insulin level (0.01 ± 0.00 ng/ml) compared to NC rats (1.15 ± 0.02 ng/ml)." (PMID 26786785, 2016). "With respect to patient co-morbidities, 20.2% had diabetes but only a quarter of them required insulin, 15.5% suffered from COPD and 17.1% had coronary artery disease." (PMID 27788141, 2016). "Major clinical trials of insulin-treated patients have included SMBG as part of the multifactorial interventions to demonstrate the benefit of intensive glycemic control on diabetes complications." (PMID 27625706, 2016). "Insulin reduced MTMR7 protein levels in human CRC cell lines, and CRC patients with type 2 diabetes mellitus (T2DM) or loss of imprinting (LOI) of insulin-like growth factor 2 (IGF2) had an increased risk for MTMR7 loss." (PMID 27409167, 2016). "STZ injection significantly induced hyperglycemia, increased INS, and reduced body weight, suggesting the development of diabetes." (PMID 26881260, 2016).
diabetes (continued). "Most people with diabetes who inject insulin monitored their blood glucose level regularly, made overviews of these data and sent it by email to their practice nurse." (PMID 27391471, 2016). "Among those with diabetes, most (20/22, 91%) were on oral antidiabetes medication and few (4/22, 18%) were on insulin." (PMID 27314047, 2016). "Less than 10% of the patients interviewed used insulin either singly or in combination with an oral hypoglycaemic agent for their diabetes management." (PMID 27559312, 2016). "Here in we report on the effects of UT on glucose homeostasis and insulin signaling in skeletal muscle of a robust pre-diabetes model; high fat fed C57BL/6J mice." (PMID 26916435, 2016). "A high (supraphysiological) dose of exogenous insulin is often required in the treatment of diabetes to achieve normoglycemia." (PMID 26939025, 2016). "We now identify the hepatic TSC22D4 as a potent regulator of insulin sensitivity in both murine and human diabetes, acting—at least in part—through the secreted factor lipocalin LCN13." (PMID 27827363, 2016). "The estimates of this prevalence is rather imprecise as some have taken insulin use as the definition for diabetes while others excluded technical failures or acute rejection to this assessment." (PMID 28702248, 2016). "Accordingly, understanding the temporal relationship betweenHNF4A gene dosage and insulin secretion is fundamental to managing pregnancy as well as neonatal and young-onset diabetes and T2D." (PMID 27508066, 2016). "We report a case in which switching to liraglutide therapy ameliorated both the symptoms of insulin allergy with hypereosinophilia and the characteristics of insulin antibodies in patients with type 2 diabetes mellitus." (PMID 27456688, 2016). "New technologies and the availability of insulin analogues led to major changes in the management of diabetes in children and adolescents." (PMID 27532627, 2016). "Due to the increasing prevalence of diabetes and insulin resistance, a main objective of this article is to make a critical review of physiological mechanisms regulated by insulin both in vasculature and in the heart." (PMID 27014078, 2016). "As diabetes duration increases, insulin granule density decreases and glycogen accumulates to such an extent that it causes gross distortion of β-cell ultrastructure." (PMID 27882918, 2016). "Multivariate logistic regression analysis for predictive markers of progression to insulin-requiring diabetes." (PMID 27177031, 2016). "Of all those who had a prior diabetes diagnosis, 34.0% in Zambia and 40.6% in Western Cape were on diabetes treatment consisting of either dietary management, hypoglycaemic tablets or insulin therapy." (PMID 27485851, 2016). "Diabetes mellitus is a group of metabolic diseases that are characterized by hyperglycemia, resulting from defects in insulin secretion, insulin activity, or both." (PMID 27795960, 2016). "Insulin is one of the main treatments for diabetes, and the bioavailability of oral insulin is limited by the gastrointestinal tract." (PMID 30979124, 2016). "Data regarding the long-term clinical outcomes in patients with insulin-treated type 2 diabetes mellitus (ITDM) revascularized by either coronary artery bypass surgery (CABG) or percutaneous coronary intervention (PCI) are still controversial." (PMID 26739589, 2016). "To date, INS studies have focused only on regulating glucose levels despite the diverse evidence suggesting that the immunological functions of INS are also important for diabetes (26, 29, –, 31)." (PMID 27226621, 2016). "Type 2 diabetes mellitus (T2DM) is an endocrine disease characterized by impaired insulin excretion by the pancreas and insulin resistance of body tissues." (PMID 27190641, 2016). "In the group with higher diabetes duration, obese individuals had lower insulin doses per body weight." (PMID 27011769, 2016).
diabetes (continued). "Visfatin is a new adipocytokine mainly secreted by visceral adipose tissue with similar effects of insulin, and a possible role in development of diabetes and inflammatory reactions." (PMID 28197509, 2016). "Information regarding diabetes management and control were obtained during first, second, and third trimesters, including HbA1c, fasting plasma glucose levels, diabetes medications (oral hypoglycemics and insulin), and any maternal medical complications." (PMID 31448371, 2016). "Among other findings, they demonstrated a similar intensity of cardioprotection between patients with and without diabetes, although they found lower protection in patients with diabetes who were taking insulin or oral antidiabetic medications." (PMID 27656659, 2016). "One year after the excision of the pancreatic head and tail, the patient developed diabetes, needing insulin therapy." (PMID 27928440, 2016). "Undoubtedly, understanding key events in these pathways is crucial for any effort to harness the protective effects of autocrine insulin signaling for the treatment of diabetes." (PMID 27526875, 2016). "Women who received prenatal care, were treated with insulin during pregnancy, or completed a postpartum visit were also more likely to receive a postpartum diabetes screening." (PMID 27570545, 2016). "Distribution of differences in numbers of anti-hypertensive medications prescribed between baseline and follow-up in Telescot diabetes trial participants by trial arm and initiation of insulin during follow-up." (PMID 27458809, 2016). "Diabetes treatment in patients with diabetic kidney disease is challenging, in part because of progression of renal failure-related changes in insulin signaling, glucose transport and metabolism, favoring both hyperglycemic peaks and hypoglycemia." (PMID 26872083, 2016). "Hyperglycemia and low insulin levels are hallmarks of T1D and key factors in the pathophysiology of diabetes complications." (PMID 27159053, 2016). "To evaluate the onset of diabetes in Akita animals, we followed changes in blood glucose in a cohort of mice while simultaneously measuring serum insulin levels." (PMID 28702245, 2016). "Due to the low availability of refrigerators, 32 % of our patients with diabetes store their insulin in a pot of water which is kept cool by use of charcoal to absorb heat." (PMID 27246505, 2016). "After we excluded item 6 in the general diabetes subscale and item 19 in the insulin-use subscale from the Rasch models, the P-values for the goodness-of-fit tests increased to 0.18 and 0.7, respectively." (PMID 27366112, 2016). "In fact, noninvasive transdermal delivery of insulin has received great attention due to diabetes treatment, one of the most costly diseases in all patient populations and age groups." (PMID 27322539, 2016). "Diabetes is a metabolic disease characterized by defects in insulin secretion, insulin sensitivity, or both." (PMID 27895622, 2016). "On the one hand, loss of pancreatic beta cells, which is observed in diabetes mellitus type 1 and in advanced stages of diabetes mellitus type 2, leads to decreased insulin production." (PMID 26824039, 2016). "Further studies are warranted to explore insulin dosing in patients with diabetes, during which meals are controlled and glucose intensely monitored." (PMID 27457238, 2016). "Using human pluripotent stem cells (hPSCs) to develop islet-like structures with insulin-producing ß cells for the treatment of diabetes is challenging." (PMID 27731367, 2016). "The genetic regulation of metabolic phenotypes (i.e., metabotypes) in type 2 diabetes mellitus occurs through complex organ-specific cellular mechanisms and networks contributing to impaired insulin secretion and insulin resistance." (PMID 27716393, 2016). "Subsequently, this technique was utilized to produce the rapid-acting, long-acting insulin formulation based on phospholipid complex loaded PHBHHx nanoparticles (INS-PLC-NPs) for diabetes treatment." (PMID 27379249, 2016).
diabetes (continued). "Diabetes mellitus type 1, or type 1 diabetes, is a widespread disease where individuals are unable to produce the insulin necessary to process blood glucose because of an autoimmune response which destroys the body’s insulin-producing beta cells." (PMID 28191438, 2016). "Pioglitazone, a thiazolidinedione (TZD) commonly used in the treatment of diabetes due to its ability to improve insulin sensitivity and reverse hyperglycemia, was ineffective in reversing the diabetes-induced changes on lysosomal enzymes." (PMID 25976368, 2016). "In fact, an intrinsic susceptibility of the β cell to functional exhaustion-commonly referred to as ‘β-cell failure'-sets apart individuals who go on to develop diabetes from those that, at the same level of insulin resistance, do not3." (PMID 27572106, 2016). "Diabetes mellitus (or simply called diabetes) is a metabolic disorder with chronic hyperglycemia resulting from defects in insulin secretion and/or action." (PMID 28018919, 2016). "How to maintain and promote glucose-mediated insulin secretion is one of the major issues for diabetes therapy." (PMID 28018473, 2016). "Its benefits have been reported in streptozotocin (STZ)-induced diabetes in mice models by stimulation of insulin secretion." (PMID 26862533, 2016). "The markers examined included fasting glucose, insulin, adiponectin, and glycated albumin, as well as body mass index (BMI), use of medications, and history of diabetes." (PMID 27830830, 2016). "In the patient with nesidioblastosis, using intraoperative portal vein insulin assay combined with occlusion of the pancreas, an appropriate amount of pancreatic tissue was resected thereby avoiding recurrence and diabetes." (PMID 27367988, 2016). "In primary care, diabetes education is mostly delivered in individual face-to-face sessions at the patient’s home and focuses mainly on training in self-administration of insulin and analogues." (PMID 27727281, 2016). "The treatment of diabetes mellitus includes diet, therapy with insulin and/or oral hypoglycemic agents and pancreas transplantation or pancreatic islets." (PMID 27547752, 2016). "During the past 10 years, significant technological advances in hESC/iPSC biochemistry have provided a roadmap to generate sufficient quantities of glucose-responsive, insulin-producing cells capable of eliminating diabetes in rodents." (PMID 28702240, 2016). "One participant revealed that their prior knowledge base about patients with diabetes starting on insulin was in fact opposite to the actual patient perspective depicted in the comic." (PMID 27520824, 2016). "While insulin independence is a realistic therapeutic goal in feline diabetes, remission is dependent on achieving glycemic control quickly and, without intensive monitoring, high insulin doses increase the risk of hypoglycemia." (PMID 27766967, 2016). "Exposures Diabetes drugs (glitazones, gliptins, metformin, sulphonylureas, insulin, other) alone and in combination." (PMID 27413012, 2016). "Other biomarkers, such as measures of C-peptide and islet cell and anti-insulin antibodies can be used to identify individuals who may be susceptible to diabetes and, though it is not currently routine clinical practice, they can also be used to aid classification of diabetes." (PMID 28082906, 2016). "Considering that insulin administration only postpones complications, new approaches to cure diabetes or provide sustained therapeutic outcome are needed." (PMID 27073927, 2016). "Studies have shown that excessive TG accumulation in nonfat tissue has been known to have a toxic effect on cells and to reduce sensitivity to insulin, eventually leading to diabetes and metabolic syndrome." (PMID 27843952, 2016). "One of the studies was focused on the role of miR-7 in pancreatic β-cell function and generated a miR-7 conditional knockout mice using Cre/Lox system (miR7a2fl/fl mice) which developed diabetes due to impaired insulin secretion and β cell differentiation." (PMID 27917109, 2016).